PIK3CG (phosphatidylinositol-4,5-bisphosphate 3-kinase catalytic subunit gamma)
Diseases named in the same sentence as PIK3CG in open-access papers (continued):
Sharing a sentence is not in itself a finding about the gene and the disease.
glioblastoma (9 papers, 2019 to 2025). The most malignant astrocytic tumor (WHO grade IV). "To ascertain the expression of PIK3CG in glioblastoma and normal brain tissues, we examined the mRNA expression of PIK3CG in 5 normal brain tissues and 156 glioblastoma samples from the UALCAN database." (PMID 39877641, 2025). "Meanwhile, the overexpression of PIK3CG is closely correlated with poor overall survival, disease-specific survival, and progression-free interval of glioblastoma patients." (PMID 39877641, 2025). "The findings demonstrated that glioblastoma samples had considerably greater mRNA levels of PIK3CG than normal brain tissues (P=2.67E-6)." (PMID 39877641, 2025). "Furthermore, we observed that PIK3CG was the maximum differential expressed gene between the plinabulin-treated group and the control group in glioblastoma." (PMID 39877641, 2025). "Our study first demonstrated that plinabulin might be a potential inhibitor of PIK3CG, and served as an anti-glioblastoma agent." (PMID 39877641, 2025). "Similarly, the protein level of PIK3CG was also elevated in glioblastoma compared to normal brain tissues based on the UALCAN database (normal: n=10 vs glioblastoma: n=99, P=8.35E-7)." (PMID 39877641, 2025). "By contrast, in spheroids derived from glioblastoma 14-60-4, the Cdkn2a and Mki67 mRNA levels were unchanged, and the transcription rates for Pik3cg, Pten, and Abcb1b increased dramatically, while Sox2 expression decreased, reaching minimal values recorded in the whole experiment." (PMID 38672482, 2024). "In this study, PIK3CG was significantly down-regulated in plinabulin-treated group compared with non-treated group, and we first demonstrated that plinabulin was regarded as a novel PIK3CG inhibitor and might be an efficacious anti-cancer agent in glioblastoma treatment." (PMID 39877641, 2025). "PIK3CG, SRC, AURKA, CDK7, and PLAT might be key molecular targets of plinabulin in glioblastoma." (PMID 39877641, 2025).
leukemia (8 papers, 2017 to 2025). A malignant (clonal) hematologic disorder, involving hematopoietic stem cells and characterized by the presence of primitive or atypical myeloid or lymphoid cells in the bone marrow and the blood. "PIK3R5 and PIK3CG, which encode a p101 regulatory and p110 catalytic subunit of PI3Kγ complex, are essential for the survival of a leukemia subset including blastic plasmacytoid dendritic cell neoplasm (BPDCN) and AMLs with high expression of PIK3R5 via a genome-wide CRISPR interference screening." (PMID 39507412, 2024). "Further analysis suggests a dependency of PIK3R5 and PIK3CG exclusively in leukemia cells and confirms an expression pattern of PIK3R5 and PIK3CG specifically enriched in BPDCN and a subset of AML compared with most AML cell lines." (PMID 39507412, 2024). "Another example of the gene network architecture of leukemia emerges by tracking up- and downstream interconnections of the genes PIK3CG (DEG-DMG) and PIK3CD (a DMG network hub) from the PI3K/AKT signaling pathway (enriched in the set of DEG-DMGs)." (PMID 32034170, 2020). "If PIK3CG is indeed involved in drug resistance in leukemia cells, it is reasonable to hypothesize that the low expression levels we observed would not generate chemotherapy resistance." (PMID 35445848, 2022).
Obesity (8 papers, 2014 to 2025). Accumulation of substantial excess body fat. "In our search for genes that specifically increase the risk of obesity in the course of ADHD, we found that the polymorphism of the PIK3CG gene (rs12667819) was associated with the risk of excess body weight in the control group." (PMID 34573389, 2021). "Obesity, PIK3CG/PI3Kγ (phosphatidylinositol-4,5-bisphosphate 3-kinase catalytic subunit gamma) ablation, ZRANB1 (zinc finger RANBP2-type containing 1), and ADORA2A-AS1 (ADORA2A antisense RNA 1) all contribute to HCC development." (PMID 39463763, 2024). "In the post-HCT group we found significantly lower expression of AGTR2, FLJ32810, NR3C2 and TMEM133 genes, and significantly higher expression of BAT2D1, MOV10, PIK3CG and WNK1 genes compared with the obesity control group." (PMID 33927307, 2021). "However, while virtually all PI3KγNest mice were protected from diet-induced obesity, PIK3CG’s Exon-3/Exon-1 ratio, was not consistently reduced in the BAT of all mice." (PMID 39811649, 2025).
diabetes (6 papers, 2012 to 2025). "Three of these—IL-6, NFkB and PIK3CG—have been linked with peri-implantitis and diabetes mellitus type 2." (PMID 37232785, 2023). "In diabetes mellitus, these signals can be dysregulated via one or several of the proteins driving insulin signaling (AKT1, PIK3R1, INSR, PPARG, and PIK3CG)." (PMID 41011980, 2025).
type 2 diabetes (6 papers, 2015 to 2026). "Studies related to the PIK3CG gene were mainly focused on signal transduction of inflammation, and p110γ is a major driver of metabolic diseases, such as fatty liver disease and type-2 diabetes." (PMID 35464836, 2022). "In this work, we investigated the impact of common genetic variation in the PIK3CG locus, represented by 10 non-linked non-coding tagging SNPs, on inflammatory traits and inflammation-related metabolic traits in individuals at increased risk for type-2 diabetes." (PMID 26658747, 2015).
atherosclerosis (5 papers, 2014 to 2024). A disease characterized by the build-up of fatty material and calcium deposition in the arterial wall resulting in partial or complete occlusion of the arterial lumen. "The regulatory effects of miR-146b-3p on VSMCs are partly dependent on PIK3CG, and miR-146-3p and PIK3CG are promising targets for the treatment of atherosclerosis." (PMID 34115567, 2021). "Our results do not confirm association of ABO rs579459, PPAP2B rs17114036, ADAMTS7 rs3825807, PIK3CG rs17398575, and EDNRA rs1878406 polymorphisms with subclinical atherosclerosis and CV disease in RA patients." (PMID 24795506, 2014). "Therefore, miR-146b-3p/PIK3CG may be a potential target for the treatment of atherosclerosis." (PMID 34115567, 2021). "Certainly, studies addressing the effects of the PIK3CG SNPs on HDL function and turnover could help defining their contribution to atherosclerosis and cardiovascular disease." (PMID 26658747, 2015).
endometrial cancer (5 papers, 2014 to 2026). Primary or metastatic malignant neoplasm involving the endometrium (mucous membrane that lines the endometrial cavity). "Consequently, mutation rates for PIK3CA are at least 10-fold higher than PIK3CB/PIK3CD/PIK3CG in solid tumours such as breast and endometrial cancer (TCGA Research Network)." (PMID 40360883, 2025).
Hypertension (5 papers, 2019 to 2022). The presence of chronic increased pressure in the systemic arterial system. "In support of this, a single nucleotide polymorphism (SNP) in a region flanking the p110γ (PIK3CG) gene locus in humans was shown to influence pulse pressure and mean arterial pressure, and potential risk of cardiovascular events including hypertension, coronary heart disease and stroke risk scores." (PMID 32002690, 2020). "Of the genes overexpressed in patients before or after HCT, WNK1 is associated with a monogenic type of hypertension, while BAT2D1, MOV10, PIK3CG are genetic variants associated with BP5,25." (PMID 33927307, 2021). "PIK3CG plays important roles in immunity, hypertension, longevity, and circulation." (PMID 30885136, 2019).
colon carcinoma (4 papers, 2017 to 2023). "Beside small molecules, the combination of plant extracts including resveratrol targeted AKT1 and quercetin targeted PIK3CG were proved to be useful for colon cancer." (PMID 32523951, 2020). "PIK3CD is mostly expressed in white blood cells and B cells and is crucial for the survival and maturation of B cell follicles, while PIK3CG expression is inversely correlated with colon cancer growth, despite the fact that PIK3CG levels are connected to cancer growth." (PMID 37176098, 2023).
pancreatic cancer (4 papers, 2014 to 2024). "Although PIK3CG is expressed mainly in hematopoietic cells, it was reported to be present at high levels in human pancreatic cancer tissue." (PMID 31112530, 2019). "Genetic or pharmacologic downregulation of PIK3CG altered the transcriptional program of tumor-infiltrating macrophages to promote cytotoxic T cell infiltration of pancreatic tumors, thus extending survival of the mice." (PMID 31112530, 2019). "However, unlike ablation of Pik3ca in KPC tumor cells, all of the animals with downregulated PIK3CG eventually died from pancreatic cancer progression." (PMID 31112530, 2019). "Importantly, PIK3CG contains the second highest scoring predicted driver mutation among the set of genes not previously identified as a driver in pancreatic cancer." (PMID 25360116, 2014). "Signaling by PIK3CG and PIK3CD in leukocytes, but not in tumor cells, can affect how the immune system responds to tumors in murine models, including pancreatic cancer." (PMID 31112530, 2019).
breast tumors (3 papers, 2019 to 2024). "Bioinformatics analysis in our study indicates that the expression of PIK3CG, AKT, and BCL2 in TNBC tissues is significantly higher than that in adjacent healthy tissues and in hormone receptor-positive breast tumor tissues." (PMID 31680955, 2019).
influenza (3 papers, 2011 to 2024). An acute viral infection of the respiratory tract, occurring in isolated cases, in epidemics, or in pandemics; it is caused by serologically different strains of viruses (influenzaviruses) designated A, B, and C, has a 3-day incubation period, and usually lasts for 3 to 10 days. "Surprisingly, although influenza infection was definitely inhibited in Pik3cg-deficient cells, Akt phosphorylation was induced by virus exposure for 6 hours." (PMID 21283725, 2011). "Here we showed for the first time a genetic association of PIK3CG SNPs on influenza protection." (PMID 29867955, 2018).
medulloblastoma (3 papers, 2021 to 2025). A malignant, invasive embryonal neoplasm arising from the cerebellum. "PIK3CG has also been established as a candidate target for managing certain cancers, including Kaposi’s sarcoma, medulloblastoma, and ALL." (PMID 40070829, 2025). "At present, there is little research on PIK3CG, but it is found that in medulloblastoma, the overexpression of PIK3CG contributes to the proliferation of medulloblastoma cells and improves resistance to cisplatin therapy." (PMID 36065261, 2022). "Their validation experiments indicate that the silencing of ATR, LYK5, MPP2, PIK3CG, PIK4CA, and WNK4 increases the effects of cisplatin in medulloblastoma cell lines." (PMID 33525637, 2021).
rheumatoid arthritis (3 papers, 2014 to 2023). A chronic, systemic autoimmune disorder characterized by inflammation in the synovial membranes and articular surfaces. "Although the role of PIK3CG in AS has not been confirmed, its inhibitors played an important role in treating autoimmune diseases such as rheumatoid arthritis, and its role in AS seemed credible." (PMID 36468006, 2022).
thymic carcinoma (3 papers, 2019 to 2025). Thymic carcinoma (TC) is a type of thymic epithelial neoplasm characterized by a high malignant potential. "Further analysis found different mutations across multiple PI3K subunit genes in another cell line and several primary thymic carcinoma samples, including two catalytic subunits (PIK3CA and PIK3CG) and another regulatory subunit (PIK3R4)." (PMID 39538003, 2025).
acute coronary syndrome (2 papers, 2017 to 2020). Signs and symptoms related to acute ischemia of the myocardium secondary to coronary artery disease. "As we have already reported, the rs342286 variant of the PIK3CG gene is associated with a younger age of patients with acute coronary syndrome." (PMID 33076381, 2020). "Associations between prognosis of acute coronary syndrome and PIK3CG rs1129293 and rs17398575 polymorphisms." (PMID 28885323, 2017).
acute myeloid leukemia (2 papers, 2021 to 2026). Acute myeloid leukemia (AML) is a group of neoplasms arising from precursor cells committed to the myeloid cell-line differentiation. "PIK3CG expression is bone marrow restricted, and its inhibition can block AKT signaling and suppress acute myeloid leukemia." (PMID 41481427, 2026).
asthma (2 papers, 2021 to 2024). "Among the genes involved in these important signaling pathways, HSPA1A, PIK3CG and PIK3R6 seemed to be associated with moderate asthma, while MAPK13 and MMP9 appeared to be associated with severe asthma." (PMID 39088141, 2024). "The expression of HSPA1A, PIK3CG and PIK3R6 was associated with moderate asthma, while MAPK13 and MMP9 were associated with severe asthma." (PMID 39088141, 2024). "The expression of HSPA1A, PIK3CG and PIK3R6 in the same 10 and 4 pathways was then verified, while the expression of MAPK13 and MMP9 related to severe asthma was also confirmed." (PMID 39088141, 2024). "Overall, this study discovered a total of five genes, including HSPA1A, PIK3CG, PIK3R6, MAPK 13 and MMP9, as potential biomarkers of moderate or severe asthma." (PMID 39088141, 2024). "PIK3CG and PIK3R6, though having no known role in asthma, was verified in the present analysis as well as other published datasets, which were used as potential novel biomarkers or therapeutic targets." (PMID 39088141, 2024).
autism (2 papers, 2014 to 2020). Persistent deficits in social interaction and communication and interaction as well as a markedly restricted repertoire of activity and interest as well as repetitive patterns of behavior. "Single nucleotide polymorphisms in PIK3CG, TSC1/2, which is mutated in the autism spectrum disorder tuberous sclerosis (TS), and INPP1, inositol polyphosphate-1-phosphatase, were shown to be in linkage disequilibrium in patients with autism." (PMID 24592210, 2014).
cognitive decline (2 papers, 2016 to 2024). "We showed that a subset of these proteins was associated with cognitive decline and levels of AD and neurodegeneration plasma biomarkers, including PIK3CG, PACSIN2 and PRKCB." (PMID 39143319, 2024).
dilated cardiomyopathy (2 papers, 2019 to 2020). Cardiomyopathy which is characterized by dilation and contractile dysfunction of the left and right ventricles. "Coding exons of LAMB1, LAMB4 and PIK3CG were screened in dilated cardiomyopathy." (PMID 33041871, 2020).
hepatocellular carcinoma (2 papers, 2020 to 2022). A malignant tumor that arises from hepatocytes. "In the current studies, the exploration and further value of PIK3CG in hepatoma may be lower than ESR1." (PMID 35872841, 2022).
myeloid tumor (2 papers, 2018 to 2022). "Among them, the PIK3CG gene, which encodes the catalytic subunit of phosphoinositide 3-OH-kinase-γ (PI3Kγ) namely p110γ, is located in chromosome band 7q22 and is often missing in myeloid malignancies." (PMID 30181715, 2018).
oral cancer (2 papers, 2021). "To determine the involvement of host Pik3cg in the response against HNSCC, we injected an aggressive murine oral cancer cell line MOC2 into the right buccal mucosa of both WT and Pik3cg−/− C57BL/6 mice." (PMID 33668795, 2021).
osteosarcoma (2 papers, 2014 to 2024). A usually aggressive malignant bone-forming mesenchymal neoplasm, predominantly affecting adolescents and young adults. "Compared to the sham group, the SNL group had higher gene expression levels of Gadd45g (growth arrest and DNA-damage-inducible 45 gamma) and Fos (FBJ osteosarcoma oncogene), while it had lower gene expression levels of Igf1, Ccl2, Hdac2, Rtn4rl1, Nfkb2, Gpr84, Pik3cg, and Abcc8." (PMID 38790607, 2024).
Peri-Implantitis (2 papers, 2019 to 2023). An inflammatory process with loss of supporting bone in the tissues surrounding functioning DENTAL IMPLANTS. "Among these top 20 hub genes, three genes (IL6, NFKB1, and PIK3CG) were common to peri-implantitis and T2DM, thus can be regarded as the potential cross-talk genes." (PMID 31275749, 2019). "Exploration of available transcriptomic datasets revealed IL-6, NFKB1, and PIK3CG expression along with the IL-17 signaling pathway as top candidate molecular linkage mechanisms between peri-implantitis and T2DM." (PMID 31275749, 2019). "Three hub genes (IL-6, NFKB1, and PIK3CG) had the highest degree in PPI networks of both peri-implantitis and T2DM." (PMID 31275749, 2019). "Three common or cross-talk genes; IL-6, NFKB1, and PIK3CG, were noted among the top 20 hub genes in the PPI networks of T2DM and peri-implantitis." (PMID 31275749, 2019).
Sepsis (2 papers, 2022 to 2023). Sepsis is defined as life-threatening organ dysfunction caused by a dysregulated host response to infection. "This study predicted a total of 109 drug targets based on the Drugbank23 database using the structure of MEL, which yielded three shared sepsis‐related genes (PIK3CG, ADA, and MAPKAPK3)." (PMID 36684068, 2023). "Our published study showed that genetic deletion of Pik3cg in lung ECs interfered with vascular repair and resolution of inflammation following sepsis-induced inflammatory vascular injury." (PMID 34986352, 2022). "Additionally, PIK3CG‐governed signaling cascade plays an important role in the etiology of sepsis and septic myocardial injury." (PMID 36684068, 2023). "Moreover, PIK3CG‐governed signaling cascade plays an important role in the etiology of sepsis and septic myocardial injury." (PMID 36684068, 2023). "Importantly, in vivo and in vitro experiments showed that MEL alleviated sepsis and septic myocardial injury by inhibiting PIK3CG‐related signaling." (PMID 36684068, 2023). "In addition, PIK3CG showed the strongest binding affinity with MEL among the three common targets shared between MEL targets and sepsis targets." (PMID 36684068, 2023).
Stroke (2 papers, 2023 to 2024). Sudden impairment of blood flow to a part of the brain due to occlusion or rupture of an artery to the brain. "The results showed that 6 genes filtered with optimal lambda value were identified as diagnostic characteristic genes in stroke, namely, HAS3, VIM, ZFP36L2, CPQ, F5, and PIK3CG." (PMID 38649659, 2024). "After taking the intersection of SCFA metabolism-related genes and the co-expression WGCNA modules of stroke, 10 SCFA-related hub genes were obtained, and 6 of them showed high diagnostic efficacy through LASSO regression and ROC analysis, including HAS3, VIM, ZFP36L2, CPQ, F5, and PIK3CG." (PMID 38649659, 2024). "In addition, the genome-wide significant stroke risk locus rs7974266 was upstream of differentially expressed gene PTPN11, rs12539561 was downstream of differentially expressed gene PIK3CG, and the 3-prime UTR variant rs42035 was downstream of differentially expressed outcome gene CDK6." (PMID 36691064, 2023).
viral infection (2 papers, 2019 to 2025). "Depletion of kinase PIK3CG, which mainly mediates cellular signalling transduction, exhibited an inhibitory effect on virus infection." (PMID 31132962, 2019).
antibody deficiency (1 paper, 2026). "Pathogenic variants in PIK3CG disrupt PI3K signaling, leading to immune dysregulation characterized by antibody deficiency, excessive T cell infiltration in the lungs/intestines, and significantly disrupted levels of T regulatory cells." (PMID 41216504, 2026).
chloroma (1 paper, 2021). "The backward elimination procedure identified RUNX1T1, MAPK3, PIK3CG, TCF7L1, GRB2, and MTOR as the empirical drivers of the association with chloroma." (PMID 33882829, 2021).
coagulopathy (1 paper, 2020). "Analysis of the targets overlapped such as PTGS1, PTGS2, PIK3CG, and PECAM1 in the pathological processes of hemorheological abnormality and coagulopathy implied that inflammation and immunity were also important for QS-BSS which need further study." (PMID 32190085, 2020).